TYR (tyrosinase)
Diseases named in the same sentence as TYR in open-access papers (continued):
Sharing a sentence is not in itself a finding about the gene and the disease.
melanoma (continued). "Conversely, the nitrite contents produced by fibroblasts correlated positively with melanin production and intracellular tyrosinase activity in melanoma cells." (PMID 38999635, 2024). "At the cellular level, it was demonstrated that tyrosinase activity in mouse melanoma B16 cells was significantly inhibited after the cells were treated with LFP at concentrations of 50 μg/mL and 100 μg/mL (without cytotoxicity) (p < 0.05 and 0.01)." (PMID 39199283, 2024). "By inhibiting tyrosinase, it is possible to regulate melanin production, thereby enabling the skin to achieve a lighter tone or alleviate skin conditions such as melanoma." (PMID 39330301, 2024). "They repress the MITF expression, reduce the cell growth, and inhibit the TYR activity in human melanoma cells." (PMID 39000342, 2024). "In 2010, a DNA tyrosinase vaccine (Oncept®, Boehringer Ingelheim Animal Health USA Inc., Duluth, GA, USA) was developed for dogs affected by melanoma, but its efficacy remains contentious." (PMID 39728968, 2024). "For example, integrating with trimetallic Au@Ag-Pt nanoparticles enable dual-mode SERS and colorimetric detection of tyrosinase, showing promise for melanoma screening." (PMID 40771575, 2024). "BNT111, an investigational lipoplex-formulated mRNA-based therapeutic cancer vaccine encoding melanoma TAAs NY-ESO-1, tyrosinase, MAGE-A3, and TPTE, is undergoing clinical testing in adults." (PMID 38890171, 2024). "For example, N-Acetyl-4SCAP (NAcCAP), which is a substrate of mushroom tyrosinase, found a use for melanoma cell cytotoxicity." (PMID 39519055, 2024). "Sericin inhibits tyrosinase activity and promotes cell proliferation that can be supportive and useful in melanoma treatment." (PMID 38732075, 2024). "Analyses comparing protein expression between skin and uvea melanomas indicate tumor antigens like tyrosinase, melan-A, and SOX10." (PMID 38392052, 2024). "Given that cutaneous melanoma predominantly occurs on the skin surface, highly sensitive detection of TYR concentrations in the skin is of critical importance for early clinical screening of melanoma." (PMID 38667195, 2024). "Our study enriched the function study of human tyrosinase, suggested promising drug candidates for the treatment of hyperpigmentation and malignant melanoma, and provided two potential whitening functional agents." (PMID 39195491, 2024). "We then assessed the effect of MITF silencing on miR-579-3p, ZFR and TYR expression levels in three different melanoma cell lines (i.e. LOX IMVI, WM266 and M14)." (PMID 38472212, 2024). "Overaccumulation of melanin or overexpression of tyrosinase (TYR) can lead to a variety of skin disorders, including wrinkles, aging skin spots, melasma, freckles, moles, and, in severe cases, melanoma." (PMID 38586368, 2024). "Young adult melanomas expressed tyrosinase (96.8%), NY-ESO-1 (19.4%), MAGE-A3 (19.4%), and TPTE (3.2%)." (PMID 38890171, 2024). "We reported the effect of tyrosinase knockdown using siRNA on the cytotoxicity of RD, MBEH, and 4-TBP in mouse B16BL6 melanoma cells, and found that some leukoderma-inducing phenols exhibited tyrosinase-dependent cytotoxicity." (PMID 39337478, 2024). "Studies on the role of tyrosinase in melanoma have evolved significantly over the years as detection techniques have advanced." (PMID 39766118, 2024). "Various investigations have determined that the enzyme tyrosinase plays an important role in the formation of melanin present in pigmented lesions such as melanoma." (PMID 39517908, 2024). "In the initial phase, the extract’s ability to inhibit tyrosinase in melanoma cells was demonstrated." (PMID 38474692, 2024). "Among them, linalyl acetate inhibits melanin contents by downregulating tyrosinase activity in α-MSH-induced B16 melanoma." (PMID 38791435, 2024). "Among them, α-pinene and D-limonene attenuate melanogenesis by downregulating tyrosinase activity in FSK-stimulated B16F10 melanoma." (PMID 38791435, 2024).
melanoma (continued). "Our study highlights the expression profile of TPTE in pediatric and adult melanomas and describes TPTE as the second most frequently expressed TAA in pediatric melanomas after tyrosinase." (PMID 38890171, 2024). "-Inhibits tyrosinase gene expression and melanine accumulation in melanoma cells.-Decreases the phosphorylation levels of Akt and p38 MAPK and EMT hepatocellular carcinoma cells." (PMID 38397559, 2024). "Consistent with previous findings, we have demonstrated that STIG inhibits α-MSH-induced melanin, tyrosinase activity, and iNOS, and NO levels in melanoma cells." (PMID 38539913, 2024). "Rhododendrol inhibits tyrosinase with a decrease in melanin synthesis in mouse B16 melanoma cells and an increase in caspase-3 levels." (PMID 39770476, 2024). "Based on IHC analysis, pediatric melanomas expressed tyrosinase (100.0%), TPTE (44.0%), MAGE-A3 (12.0%), and NY-ESO-1 (8.0%)." (PMID 38890171, 2024). "Ultimately, we sought to investigate the potential of T. himalayense NIBRFG0000505337 as a whitening agent by assessing its impact on tyrosinase, TRP-1, TRP-2 and MITF expression in α-MSH-treated B16F10 melanoma cells and elucidating the underlying mechanism." (PMID 38480002, 2024). "Their effects on the intracellular activity of tyrosinase and the melanin content were assayed in B16 melanoma cells." (PMID 39795088, 2024). "MITF, commonly expressed in melanomas, plays a major part in transformation and progression, as it regulates the progression of TYR." (PMID 39519055, 2024). "Almost all young adult melanomas expressed tyrosinase (96.8%, n = 30) and expressed the other three TAAs in notably different frequencies than pediatric melanomas." (PMID 38890171, 2024). "The high isoflavone-Sappanone A, isolated from hematoxylin, can inhibit tyrosinase activity and lead to a decrease in melanin production by suppressing the expression of tyrosinase gene in mouse B16 melanoma cells in a dose-dependent manner." (PMID 38586368, 2024). "Melanin production and intracellular tyrosinase activity assays were performed by pre-exposing melanoma cells to B. alba extracts, followed by induction with IBMX for an additional 48 h." (PMID 39335872, 2024). "Nevertheless, excessive melanin was connected to tyrosinase overexpression, which resulted in hyperpigmentation and melanoma diseases." (PMID 39598198, 2024). "Herein, we evaluated the inhibitory effect of S. flavescens extract and four prenylated flavonoids on mushroom tyrosinase in vitro, and the anti-tyrosinase and anti-melanogenesis effects of these flavonoids using cellular (murine melanoma cells) model." (PMID 39050754, 2024). "HLA peptides from MDAs, such as DCT, PMEL and tyrosinase were recurrently detected exclusively in melanoma and melanocytes." (PMID 39835134, 2024). "After EGR3 overexpression in melanoma cells, cell cycle arrest was observed in the G1 phase, accompanied by decreased levels of TYR expression and enzyme activity within the cells, resulting in reduced melanin production." (PMID 38973154, 2024). "Tumor cells in melanoma show positivity for S-100, HMB-45, vimentin, Melan-A, tyrosinase, and microphthalmia-associated transcription factor (MITF)." (PMID 39280438, 2024). "QHP has an excellent antioxidant effect and can enhance SOD activity, which effectively cleared free radicals from the A375 malignant melanoma cell line, reducing TYR activity and melanin content." (PMID 36582825, 2023). "AmIV extracts increased the activity of mushroom tyrosinase and tyrosinase present in B16F10 murine melanoma cells, whereas AmL and AmH extracts showed significant inhibitory potential." (PMID 37375348, 2023). "A-alum-1 inhibited melanin production in a dose-dependent manner in α-MSH-induced melanoma cells, alongside the suppression of tyrosinase expression and activity." (PMID 37834109, 2023).
melanoma (continued). "HLA-A2 melanoma patients vaccinated with DCs pulsed with melanoma antigen-derived peptides (gp100 and tyrosinase) show an increased number of vaccine-specific T cells." (PMID 37834126, 2023). "BNT111 encoding the antigens, tyrosinase, NY-ESO-1, MAGE A3, and TPTE, is currently being investigated in melanoma." (PMID 36830845, 2023). "Safety and tolerability of the BNT111 mRNA vaccine, which encodes four melanoma antigens: NY-ESO-1, tyrosinase, MAGE-A3, and TPTE, is under evaluation in a phase I trial (NCT02410733)." (PMID 36992220, 2023). "This study found another niosomal formulation with a lower size that enhances the anti-tyrosinase and anti-melanoma activity of GA." (PMID 38139807, 2023). "Pharmacological modulation of tyrosinase-dependent melanogenesis is a potential therapeutic approach for combatting melanoma as well as other pigmentation-related disorders." (PMID 37184042, 2023). "As for TYR (OCA1) and SLC45A2 (OCA4), patients with these mutations showed an irregular pigmentation as the most characteristic dermoscopic aspect of melanomas, despite the common tendency to develop hypomelanotic/amelanotic lesions, as previously reported." (PMID 37568588, 2023). "In our cohort, out of 115 patients referred to genetic counseling for melanoma, 25 tested positive (21.7%) for critical mutations: CDKN2A (n = 12), MITF (n = 3), BAP1 (n = 1), MC1R (n = 3), PTEN (n = 1), TYR (n = 2), OCA2 (n = 1), and SLC45A2 (n = 2)." (PMID 37568588, 2023). "In particular, certain amino acids in PMEL and TYR, which are melanocyte-specific antigens recognized by CD8+ T cells in melanoma-associated vitiligo, were better presented by AI alleles." (PMID 37339630, 2023). "Melanoma patients receiving autologous DCs electroporated with mRNAs encoding MAGE-A1, -A3, -C2, tyrosinase, MelanA/MART-1, or gp100, show DC-related adverse events but no appreciable toxicity." (PMID 37834126, 2023). "Liu-Smith and Meyskens previously reported that flavonoids inhibit melanin biosynthesis by suppressing the cAMP–PKA–CREB–MITF–tyrosinase signaling pathway, leading to excellent effects in the prevention and treatment of melanoma." (PMID 36614262, 2023). "6-methylcoumarin can increase the MITF and tyrosinase expression in B16F10 melanoma cells by inducing AKT phosphorylation." (PMID 37299026, 2023). "Compounds were then examined as tyrosinase and melanogenesis inhibitors in murine melanoma B16F0 cell line, followed by the cytotoxicity assays of these cells." (PMID 37146256, 2023). "Then, we studied the effect of extract concentration on melanin production and intracellular tyrosinase activity in B16F10 melanoma cells of these three species." (PMID 37109464, 2023). "The authors proposed that due to the TYR inhibitory activity of 35, as well as its ability to decrease melanin production in melanoma cells in a dose-dependent manner, this small molecule possesses the potential to be explored as a therapeutic agent." (PMID 37570734, 2023). "Scientific efforts have been addressed to the development of inhibitors targeting the tyrosinase enzyme as potential anti-melanoma agents due to the importance of this enzyme in melanogenesis biosynthesis." (PMID 36982292, 2023). "In this context, the current work explored the in vitro anti-melanoma, anti-melanogenic, and anti-tyrosinase effects of cannabidiol (CBD) and three minor phytocannabinoids, namely cannabigerol (CBG), cannabinol (CBN), and cannabichromene (CBC)." (PMID 37242431, 2023). "To characterize the role of CXCR2 during melanoma tumorigenesis, we generated tamoxifen-inducible tyrosinase-promoter driven BrafV600E/Pten−/−/Cxcr2−/− and NRasQ61R/INK4a−/−/Cxcr2−/− melanoma models." (PMID 37270599, 2023). "Hairpin DNA complementary to the tyrosinase mRNA was conjugated with GNPs for the successful detection of the overexpressed tyrosinase gene in melanoma cells." (PMID 38112935, 2023).
melanoma (continued). "N-propionyl-4-S-cysteaminylphenol (N-Pr-4-S-CAP) is a substrate for tyrosinase, which is a melanin biosynthesis enzyme and has been shown to be selectively incorporated into melanoma cells." (PMID 36982309, 2023). "The excellent performance of the tyrosinase bandage biosensor shows the prospect of rapid screening for melanoma." (PMID 36979525, 2023). "MAGE-A3 and MAGE-C2 are exclusively expressed in germ cells and tumor cells (including melanoma cells), while tyrosinase and gp100 are widely expressed in both tumor and normal tissue." (PMID 37726283, 2023). "N-Pr-4-S-CAP is a substrate for a melanin biosynthesis enzyme, tyrosinase, which is highly and uniquely expressed in malignant melanoma." (PMID 36982309, 2023). "It was shown that kaempferide significantly increased the expression of melanin-biosynthetic genes (MC1R, MITF, TYR, TYRP1, and DCT) and the tyrosinase activity in the B16F10 melanoma cell line." (PMID 37047297, 2023). "We have reported here the antimelanogenic and anti-tyrosinase effect of R. × damascena on the B16F10 murine melanoma cell line for the first time." (PMID 37605721, 2023). "After an in vitro enzyme binding assay reported earlier, the authors evaluated the potency of the selected remedy extracts and active ingredients, including glabridin, in the cellular anti-tyrosinase model using murine melanoma (B16F1) cells." (PMID 36770624, 2023). "The researchers found that tyrosinase staining was strongly positive in 84% of melanoma cases, including both conventional and desmoplastic melanomas." (PMID 37504268, 2023). "A study has shown that AgNPs synthesized from Fusarium incarnatum fungal extracts have an ability to inhibit tyrosinase activity (the main enzyme in the biosynthesis of melanin), in melanoma cells, in a dose-dependent manner." (PMID 37622997, 2023). "In the study, human tyrosinase-cDNA was transfected into amelanotic melanoma cell line A1059, leading to a novel melanotic cell line, TA1059." (PMID 38140004, 2023). "Later, the authors determined an IC50 value of glabridin against murine melanoma (B16F1) intracellular tyrosinase, and the glabridin IC50 value was 0.69 μg/mL." (PMID 36770624, 2023). "On the other hand, recently the effects of sulforaphane to reduce melanoma cell proliferation and to increase tyrosinase production was reported." (PMID 36768978, 2023). "All four derivatives (87a–87d) were able to inhibit melanogenesis in α-MSH stimulated B16F10 melanoma cells by reducing TYR activity." (PMID 37240442, 2023). "The occurrence and treatment of pigment disorders, malignant melanoma, albinism and senile dementia are directly related to tyrosinase." (PMID 36969838, 2023). "Several studies evaluated the expression of tyrosinase in various types of melanoma and peripheral nerve tumors using immunohistochemistry." (PMID 37504268, 2023). "Markedly high melanin synthesis in malignant melanoma cell lines is known to be because of elevated tyrosinase activity (a rate-limiting enzyme in the melanin production cycle)." (PMID 37731680, 2023). "Decursin, an effective compound of Angelica gigas Nakai, has been reported to possess protective effects against hyperpigmentation by inhibiting melanin synthesis and tyrosinase activity of B16F10 melanoma cells." (PMID 37375695, 2023). "Coumarin-based compounds have shown potential activity as anti-melanoma agents and tyrosinase inhibitors." (PMID 36982292, 2023). "Most of the studies found did not address the effect of L-DOPA treatment on the development of melanoma but numerous studies were mainly related to the in vitro testing of tyrosinase, in which L-DOPA was used as a substrate for this enzyme." (PMID 38067245, 2023). "It has been reported that alanine, glycine, phenylalanine, and aspartic acid were shown to have different effects against melanin contents and TYR activity in B16 melanoma cells according to their chemical structures or their combinations." (PMID 36969816, 2023).
melanoma (continued). "These compounds were examined in vitro for their TYR inhibition against the monophenolase activity of mTYR as well as anti-melanogenesis activities in B16F10 melanoma cells." (PMID 37570734, 2023). "A suggested dose of 100 μg of tyrosinase plasmid DNA was proposed, the same used in dog melanoma treatments." (PMID 36670786, 2023). "Immunohistochemical staining positive for protein S-100, HMB-45, Melan-A, Mart-1, and tyrosinase support the diagnosis of melanoma." (PMID 36900152, 2023). "The results suggest that the Span 60/cholesterol niosomal formulation is a suitable GA delivery system for skin problems with potent in vitro antibacterial, anti-melanoma, and anti-tyrosinase activities." (PMID 38139807, 2023). "ICB-induced vitiligo has been linked to a cross-reaction against antigens shared by normal melanocytes and melanoma cells, such as tyrosinase, MART-1, and GP100, as well as tyrosinase-related proteins 1 and 2 or tyrosinase." (PMID 37046745, 2023). "In Bomirski hamster melanoma cells, L-tyrosine supplementation not only increased melanin formation but also enhanced tyrosine hydroxylase activity and tyrosinase oxidation activity to dopa." (PMID 36901791, 2023). "Tyrosinase IHC staining can help confirm the diagnosis of melanoma and distinguish it from other types of skin cancers or benign lesions." (PMID 37504268, 2023). "Tyrosinase inhibitory activity was performed in two separate tests on mushroom tyrosinase also in melanoma cells." (PMID 37605721, 2023). "MITF has been extensively studied in melanoma cells where its transcriptional activity modulates target genes involved in pigmentation, such as TYR, MC1R, DCT, and MLANA." (PMID 37898636, 2023). "In melanoma, the protective effect of finasteride on melanogenesis via downregulation of tyrosinase, TRP-1, MITF, and ACs expression has been demonstrated, further in vivo animal experiments are required for confirmation." (PMID 37993971, 2023). "In the melanoma models used in our studies, the targeted alterations in gene expression (Braf/Pten/Cxcr2−/−) occur in tyrosinase expressing melanocytes." (PMID 37270599, 2023). "Considering the central role of tyrosinase in melanogenesis, and its relationships with the development of melanoma, efforts have been directed toward the development of drugs that inhibit its activities, such as anti-melanoma agents." (PMID 36982292, 2023). "This so-called TriMix-RNA was combined with additional mRNAs, each encoding for one of four melanoma-associated antigens (MAGE-A3, MAGE-C2, tyrosinase, or gp100), and further introduced into DCs by electroporation." (PMID 37569548, 2023). "Tyrosinase, an enzyme involved in melanogenesis in melanosomes, is also highly sensitive to primary melanoma." (PMID 37427124, 2023). "These sensors behaved well in detecting tyrosinase and thus were significant for melanoma screening." (PMID 39188558, 2023). "Nodakenin, an effective compound of Angelica gigas Nakai, showed anti-melanogenesis effects by decreasing the melanin synthesis and tyrosinase activity of B16F10 melanoma cells." (PMID 37375695, 2023). "This along with the fact that 4-S-cysteaminylphenol has zero efficacy in killing amelanotic melanoma cell lines suggest that the antimelanoma effect of 4-S-cysteaminylphenol is coordinated with oxidation by tyrosinase." (PMID 37731680, 2023). "We determined that CD11c+ cells were able to phagocytose fragments of melanoma cells since abundant tyrosinase and melanin granules were found in their cytoplasm; cytoplasmic MART-1 was also detected in these cells (data not shown)." (PMID 37691949, 2023). "The implications extend to applications in inflammation treatment and tyrosinase inhibition, suggesting that it can make a significant contribution to addressing skin conditions, including melanoma and various inflammatory diseases." (PMID 38247759, 2023).